CCND1 (cyclin D1)
Diseases named in the same sentence as CCND1 in open-access papers (continued):
Sharing a sentence is not in itself a finding about the gene and the disease.
tumor (continued). "This process of BHRF1+/SNHG8 high/miR-512-5p low/TRIM28high in EBVaGC directly enhances the activation of a set of tumor-promoting factors, such as proliferation-related genes (BCL-2, CCND1, PCNA, PARP1) and metastasis-related genes (Snail, VIM, CDH1, and CDH2)." (PMID 34722282, 2021). "Our data demonstrated that overexpression of FHL1 inhibited the proliferation, colony formation potential, and expression of CdK4 and Cyclin D1, whereas ablating FHL1 promoted proliferation and colony formation potential, suggesting that FHL1 acts as a tumor suppressor in CRC." (PMID 34335951, 2021). "The anticancer effects of AA on HCC were predicted to be associated with regulating tumor cell proliferation, apoptosis, angiogenesis, tumor invasion, and metastasis via various pathways such as the EGFR signaling pathway, ESR1 signaling pathway, and CCND1 signaling pathway." (PMID 33688369, 2021). "In the same model, an ATX-enriched diet (15 mg/kg) suppressed tumor progression via inhibition of the JAK/STAT3 signaling pathway and its downstream targets cyclin D1, MMP-2 and -9, and VEGF, preventing cell proliferation and invasion and, consequently, regulating tumor microvascular density." (PMID 34677429, 2021). "Notably, tumor sample analysis showed that RB1 protein abundance was slightly increased, while protein levels of CDK6, cyclin D3, cyclin E1, cyclin D1, SKP2, and CDK2 were significantly decreased in the combination treatment group." (PMID 34508104, 2021). "Recent studies have demonstrated that cyclin D1 (CCND1) plays a significant role in regulating the cell cycle, thereby promoting tumor proliferation, invasion, and metastasis, as well as angiogenesis and resistance to chemotherapy and radiotherapy in multiple cancer types." (PMID 34063946, 2021). "Moreover, the cell cycle is an essential factor of cell growth; the cell cycle is regulated by complexes of cyclins and cyclin-dependent kinases during cell division, Cyclin D1, CDK1, CDK2, and CDK4 are often upregulated in tumor cells." (PMID 33953676, 2021). "Tumor masses from HCC PDX mice treated with omacetaxine and negative control were utilized to prepare frozen sections, which were then stained for the c-Myc, MET, β-catenin, XIAP, and cyclin D1." (PMID 34003798, 2021). "However, a number of tumorigenic proteins like Bcl family, Mcl-1, survivin, IAP-1/2, COX-2, cyclin D1, VEGF, and MMP-9 can negate the apoptotic influence and promote tumor cell survival." (PMID 34360911, 2021). "Furthermore, the results showed that FOXC1 can promote growth of GC by modulating the tumor cell cycle, as mediated by c-MYC and cyclin D1, further supporting the role of FOXC1 in GC progression." (PMID 33987183, 2021). "Analysis of Cyclin D1 expression in primary OSCC did not reveal any difference among the three histological grades of tumours." (PMID 31983161, 2020). "In addition, in several researches, its tumor suppressive role on NOTCH1 (apoptosis induction and proliferation inhibition) and c-Myc/CCND1 (G1 arrest) has been reported." (PMID 32440325, 2020). "EZH2-mediated PRC2 activation contributes to the transcriptional silencing of tumor suppressor genes, leading to the activation of NOTCH, JAK-STAT, or β-catenin signaling pathways and upregulation of cell cycle genes, such as CDK2, CDK4, and CCND1." (PMID 33121524, 2020). "Moreover, cyclin D1 is also a key factor for VEGF transcription, which is also lower in tumor masses from mice treated with pantoprazole." (PMID 32164284, 2020). "Our results were consistent with those from in vivo experiments, that is, dramatic decreases in class I HDACs, CDK4, cyclin D1, Ki-67, and EMT-promoted protein expression and increased p21 and E-cadherin expression in tumor tissues of mice treated with magnolol or MM1." (PMID 32850418, 2020).
tumor (continued). "This molecule inhibited the cell growth of a wide variety of tumor cells (but not normal human fibroblasts), blocking them in G1/S, with the downregulation of cyclin D1 and upregulation of p21 and p27." (PMID 32933137, 2020). "Cyclin D1 overexpression leads to an imbalance in CDK activity, which accelerates cell growth (even with limited mitotic signaling), bypasses key cell cycle checkpoints, and promotes tumor growth." (PMID 32337233, 2020). "Cyclin D1 and c-Myc are common downstream molecules of the β-catenin/TCF4 complex and are related to cell proliferation, migration and invasion in a variety of tumor mechanisms 68-70." (PMID 32373221, 2020). "It has been reported that cytokines and pro-inflammatory TME promote the phosphorylation of NF-κB and the expression of proliferative (cyclin D1), metastatic (MMP-9, CXCR4) tumor-promoting proteins and inhibit apoptosis (caspase-3), which have a p65-NF-κB binding site in their promoters." (PMID 32708030, 2020). "The decreased protein amounts of p-AKT Ser 473 and cyclin D1 and increased protein amount of GSK 3β were detected by western blotting and immunohistochemical staining in the tumor tissue removed from the mice treated with 6-gingerol as compared to that removed from control untreated mice." (PMID 31832810, 2020). "Besides CCND1 and TERT, 30 additional genes were altered in at least two tumor samples in our cohort, either through SNV or SV." (PMID 33384420, 2020). "The tumor incidence and multiplicity were suppressed after GLT administration (0–500 mg/kg for 17 weeks), and the mechanism was revealed to be correlated with the inhibition of cyclin D1 and COX-2 expression in colon tissue." (PMID 32410986, 2020). "For the orthotopic transplanted tumor experiments, the JPFR extract could inhibit the growth of orthotopic transplanted tumors and downregulate the expression of c-Myc and Cyclin D1 in a dose-dependent manner." (PMID 32774415, 2020). "The expression levels of AKT, p-AKT Ser 473, GSK 3β, p-GSK 3β Ser 9, CDK4, and cyclin D1 in tumor tissue removed from the mouse groups treated or not treated with 6-gingerol were measured next." (PMID 31832810, 2020). "CJ-1383 induced breast cancer cell apoptosis in a dose-dependent manner, while inhibition of tumor growth by the phosphopeptide mimetic PM-73G occurred without apoptosis or changes in the expression of cyclin D1 or survivin in xenograft models." (PMID 32872659, 2020). "Using GBM xenografts, it is shown that invasive GBM cells, but not cells within the tumor masses, express a Cyclin D1 mostly located in the cytoplasm, and forced membrane accumulation of Cyclin D1 induces the number of invading cells." (PMID 33317149, 2020). "Moreover, EHD slowed the growth of xenograft tumours in nude mice; decreased the expression levels of STAT3, p-STAT3, and cyclin D1; and upregulated the expression level of P27." (PMID 32382281, 2020). "Indeed, CDDO-Me has also been shown to target cyclin D1, EGFR, and STAT3 signaling in PyMT tumor cells." (PMID 32300202, 2020). "IHC staining and ISH staining showed that overexpression of DILA1 led to a markedly higher expression of Ki67, Cyclin D1, and p-Rb(Ser780) but lower p-D1(Thr286) levels in the tumor that were not affected by tamoxifen." (PMID 33139730, 2020). "An integrated genomic and transcriptomic study of five patient-derived xenografts also determined that the copy numbers of CCND1 and CDKN2A are potential targets of palbociclib and may mediate the suppression of tumor growth." (PMID 33243298, 2020). "Moreover, DGCR5 overexpression significantly decreased the protein levels of proliferation marker ki-67, cell cycle regulator Cyclin D1, and mesenchymal marker TWIST, but increased the protein level of the epithelial marker E-cadherin in tumor tissues." (PMID 33085646, 2020).
tumor (continued). "First, imipramine may inhibit ERK/NF‐κB signalling transduction and thus reduced tumour progression‐related proteins expression, including MGMT, MMP‐2, MMP‐9, uPA, VEGF, Cyclin D1 and XIAP." (PMID 32149465, 2020). "This categorization resulted in the formation of three different clusters: 47 cases (57.3%) in which there was no change in CCND1 expression and 15 cases (18.3%) where CCND1 was upregulated as expected in proliferating tumor tissue." (PMID 32224897, 2020). "In consistence with our previous findings, the results showed that ATP6AP2 expression is higher in tumor tissues than that in normal tissues, moreover, level of ATP6AP2 transcripts in COAD is positively correlated with those of LRP6, CTNNB1, MYC, CCND1 and AXIN2." (PMID 32143717, 2020). "Functional studies further demonstrated that stable short hairpin RNA (shRNA)-mediated knockdown of MGLL inhibits tumor proliferation and metastasis, both in vitro and in vivo, and mechanistically, our data indicate that MGLL regulates Cyclin D1 and Cyclin B1 in LUAD cells." (PMID 33363004, 2020). "Moreover, tumour progression‐related proteins such as MMP‐2, MMP‐9, uPA, VEGF, Cyclin D1 and XIAP were all decreased by imipramine in U‐87 MG and GBM8401 cells." (PMID 32149465, 2020). "Subsequently, decreased cyclin D1 and increased cyclin D1/CDK inhibitors p21 and p27 levels are observed, suggesting that the combination therapy may inhibit tumor growth by blocking G1/S phase cell cycle progression." (PMID 32944243, 2020). "In the primary tumor, most CNV were found in MYC, CCND1, ERBB2 and CCNE1." (PMID 33298978, 2020). "In patient 10, CCND1 and TSC2 amplification were identified only in tumour #1." (PMID 31929516, 2020). "Feeding mice with an ω-6 rich diet (44% energy from safflower oil containing 76% LA) led to increased Cox-2 expression, epigenetic activation of Ptsg-2 coupled with silencing of tumour suppressor Apc and accumulation of C-JUN and Ccnd1, thus contributing to colonic inflammation and cancer." (PMID 32526973, 2020). "5-Aza-CdR interestingly decreased levels of genes that promote tumor progression, such as CCND1, MKI67, BIRC5, and BCL2, but failed to decrease MUC4 and NOTCH1." (PMID 32182826, 2020). "Given that cyclin D1 is required for tumor formation induced by HPV proteins E6 and E7, it indicated that cyclin D1 downregulation may also contribute to a better prognosis of HPV(+) patients." (PMID 32224897, 2020). "Extent of Cyclin D1 staining was graded according to percentage of positive tumor cells as diffuse (> 70%), focal (5 to 70%), and negative (< 5%)." (PMID 30736802, 2019). "Therefore, we investigated the expression of ER subtypes in human cSCC A431 cells and the effects of ER subtype activation by ER agonists on the expression of tumor markers CD55 and Cyclin D1." (PMID 31611744, 2019). "Strikingly, TERT mRNA was only expressed in the tumor with concomitant TERT promoter and BRAFV600E mutations, whereas neither differences in expression of ETS-factors nor the downstream target cyclin D1 were observed." (PMID 31391125, 2019). "CCND1 and PARP2 are reported to be involved in tumor development and act as oncogenes." (PMID 31340767, 2019). "Kaplan-Meier and multivariable Cox regression analyses were used to determine survival differences between CCND1 amplified vs. non-amplified tumours in clinically relevant patient sets, within PAM50 subtypes and within treatment-specific subgroups." (PMID 30819233, 2019). "Similarly to CCND1, expression of the cell cycle-related genes RB1 (retinoblastoma 1) and AR (androgen receptor) were also higher in luminal tumours relative to basal-like (see “AR” and “RB1”, P < 0.001 for luminal A vs. basal-like comparisons)." (PMID 30819233, 2019).
tumor (continued). "Western blot analysis revealed that cyclin D1 protein expression as well as RB phosphorylation were markedly increased at multiple time points in tumor tissue, but not in liver tissue, relative to control mice samples assayed in parallel." (PMID 31039152, 2019). "At the same time, we found that the level of CCND1 is higher in the patients without tumor recurrence compared to those patients with tumor recurrence (P < 0.001)." (PMID 31183974, 2019). "Importantly, NO signaling up-regulated the expression of cyclin D1 via activating the MAPK and PI3K/Akt-dependent c-myc activity, ultimately promoting the malignant proliferation of tumor cells." (PMID 31699997, 2019). "Tumor cells promote angiogenic activity through increases in hypoxia-inducible factor 1α (HIF-1α), vascular endothelial growth factor (VEGF), erythropoietin (EPO), cyclin D1 protein expression, which are essential for tumor growth." (PMID 30678221, 2019). "We found that CCND1 protein expression was not correlated with the age, gender, tumor size, tumor site, differentiation degree, infiltration depth (T stage), lymphatic metastasis or distant metastasis (all p > 0.05)." (PMID 31718693, 2019). "In both the control and Rapamycin treated group, the tumor cells continued to be positive for cyclin-D1 irrespective of the size of the tumor foci." (PMID 30863496, 2019). "Accordingly, we speculate that specific inhibition of cyclin D1/CDK4 activity may produce clinical benefits for GC patients who have elevated expression of cyclin D1 and CDK4 in their tumours." (PMID 30714150, 2019). "Among these genes, CCND1 and MDM2 are known to be oncogenes and CDKN2A is a tumor suppressor." (PMID 30755618, 2019). "In summary, we show that assessment of CCND1 amplification status can provide long-term independent prognostic information in patients with ER+/LN−/HER2− tumours, and novelly, within luminal A and luminal B tumours." (PMID 30819233, 2019). "Moreover, METTL3 or IGF2BP2 expression positively correlated with the SOX2 downstream genes CCND1, MYC, and POU5F1 in our independent cohort of paired CRC tumor and adjacent normal tissues from SYSUCC." (PMID 31230592, 2019). "Indeed, several genes such as CTNNB1, CCND1 and NKD1 involved in the Wnt/β-catenin signaling pathway showed increased m6A methylation in tumor tissues with respect to normal." (PMID 31870368, 2019). "Curative treatment with BMS309403 significantly decreased tumor FABP4 (p = 0.04), cyclin D1 (p = 0.02), VEGFA (p = 0.002) and VEGFR (p = 0.001) expression compared to the control group, while active caspase 3 was induced (p = 0.008) in parallel with mTOR pathway downregulation." (PMID 30575815, 2019). "RT-qPCR assays revealed that the expression of maspin affected the gene expressions of cyclin D1, p21, vimentin MMP2, and MMP9 in xenograft tumors, which suggested that maspin may modulate these genes to regulate tumor growth in vivo." (PMID 31861435, 2019). "In addition, we detected proliferation-related proteins (Ki67, Bcl-2 and cyclin D1), CSCs core genes and DNMT3B levels in tumor grafts to investigate the mechanism by which antisense inhibition of piRNA-823 reduced the tumor volume in vivo." (PMID 30979371, 2019). "Generally, the results obtained from this study demonstrated that the expression level of cyclin D1 seems to be directly related to tumor grade, while it does not seem to be related to the sex and age of the patient." (PMID 31583003, 2019). "In addition, qRT-PCR analysis of relevant gene expression levels in the isolated tumor tissues showed that the expression of UCA1, β-catenin and cyclin D1 was up-regulated, while the expression of axin was down-regulated from the UCA1 group." (PMID 31596734, 2019).
tumor (continued). "In addition, some other HIF downstream targets, such as VEGF or Cyclin D1, are strongly pro-tumor growth, whereas other HIF downstream targets such as GLUT1 or IGFBP3, are obviously tumor suppressive." (PMID 30355451, 2018). "Cyclin D1, CDK4, c-Myc, and p27kip1 contribute to tumor growth by promoting cell cycle progression." (PMID 29614812, 2018). "Alterations to cyclin D1, CDK1, CDK2, CDK4 and p16, which regulate the cell cycle, led us to speculate whether ABHD11‐AS1 affects tumour progression by regulating the protein expression of factors linked to the cell cycle." (PMID 29799152, 2018). "pRB and cyclin D1 reactivity was low (< 25% of tumor cells) or absent in 48.6% and 57.8% of OPSCC, respectively." (PMID 30189895, 2018). "Furthermore, the expression of stemness genes ABCG2, Nanog, Notch1 and Oct4 as well as Wnt-related genes CCND1, c-Jun, VEGF, and c-myc in tumor xenografts was down-regulated in shRab37 + rSFRP1 group (symbols pink vs. red)." (PMID 30158579, 2018). "Our findings of high expression of Cyclin D1 and significantly higher expression of AXIN2, LEF1 and ZNRF3 mRNA in tumours harbouring the ∆(2 + 3) deletion at a similar level to those with hot spot mutations suggest the activating nature of these deleterious mutations in ACCs." (PMID 29872083, 2018). "The results in vivo also confirmed that knockdown of NEAT1 sensitized the OS cells to DPP-induced tumor regression, delayed the tumor growth with reduced levels of Ki-67, BCL-2, and cyclin D1 signals, suggesting that NEAT1 is an oncogene and chemotherapy resistant factor in OS." (PMID 29654165, 2018). "The anti-tumor response to the combination of curcumin and OPCs in mice xenograft tumors and organoids derived from primary human CRC tumors correlated with the altered gene expressions of HSPA5, IHH, PDE3B, cyclin D1 and SEC61B." (PMID 30218018, 2018). "Because NF-κB regulates the expression of the antiapoptotic and proliferative proteins such as cyclin D1, COX-2, VEGF, and survivin, we tested whether Rg3 can modulate the expression of these gene products in tumor tissues in xenografts." (PMID 29743919, 2018). "In line with our recent results that miR‐634 functions as tumor suppressor by targeting CYR61 through Raf‐ERK signaling, van Jaarsveld MT also found that the cell cycle regulator CCND1 and Ras‐MAPK pathway components GRB2, ERK2, and RSK2 were directly repressed by miR‐634 overexpression." (PMID 29473317, 2018). "Patients whose tumor had higher CCND1 log2 copy number ratio derived no significant benefit from tamoxifen." (PMID 30041599, 2018). "E2F8 was found to be markedly overexpressed in HCC to facilitate tumor occurrence and development via activation of an E2F1/cyclin D1 signaling pathway to regulate the G1- to S-phase transition of cell cycle progression or transcriptionally suppress CDK1 to induce hepatocyte polyploidization." (PMID 30326936, 2018). "Patients whose tumor expressed a high log2 copy number ratio of CCND1 as assessed with probe 2 did not benefit from tamoxifen." (PMID 30041599, 2018). "Rhodamine (Rho123), cytochrome-c, caspase-3, P-27, cyclin D1, and autophagy cell markers were analyzed by flow cytometry to demonstrate potential cellular activity and the absence of apoptotic and tumor cell processes before and after cell differentiation." (PMID 29641603, 2018). "This synergistic effect between propranolol and sunitinib to inhibit MM proliferation was through suppressing ERK/Cyclin D1/Rb/Cyclin E pathways and inducing G0/G1/S phase arrest, rather than by inducing tumor cell apoptosis." (PMID 29416656, 2018).